MIR212 (microRNA 212)
Synonyms: hsa-mir-212; MIRN212; mir-212
Gene: MicroRNA gene on chromosome 17 (2,050,271 to 2,050,380, reverse strand). Ensembl gene ENSG00000267195.
Gene Ontology:
Biological process: negative regulation of gene expression; miRNA-mediated post-transcriptional gene silencing
Cellular component: RISC complex
Homologues: Orthologues: rat Mir212 (95% identical), pig MIR212 (90% identical), guinea pig MIR212 (82% identical), dog MIR212 (75% identical), rabbit MIR212 (73% identical), macaque MIR212 (62% identical), zebrafish dre-mir-212 (60% identical), tropical clawed frog xtr-mir-212 (58% identical). Paralogues in human: MIR132 (49% identical).
Diseases named in the same sentence as MIR212 in open-access papers:
MIR212 is named in the same sentence as 1 disease in open-access papers, as found by Europe PMC text mining. Sharing a sentence is not in itself a finding about the gene and the disease.
MIR212 shares sentences with these, for which no sentence is quoted: nasopharyngeal carcinoma (1 paper).